ENSG00000275666
Gene: Miscellaneous RNA gene on chromosome 11 (2,652,099 to 2,652,562, forward strand). Ensembl gene ENSG00000275666.
Gene Ontology:
Biological process: heterochromatin formation
Cellular component: nucleolus